EGFR (epidermal growth factor receptor)
Diseases named in the same sentence as EGFR in open-access papers (continued):
Sharing a sentence is not in itself a finding about the gene and the disease.
tumor (continued). "Tumor size, dichotomized based on the median value, was not linked with EGFR mutations (P = .367)." (PMID 22091430, 2011). "Therefore, therapeutic modulation of the HA system may contribute new anticancer strategies in tumours dependent on EGFR signalling by disruption of this feedback cycle." (PMID 21429221, 2011). "These experiments demonstrate that the inactivation of survival effector p-AKT leads to the rapid release of accumulated apoptotic potential in EGFR-addicted cancer cells, which may be an important reason that leads to the sensitivity of tumor cells to drugs that target the addicted oncogene EGFR." (PMID 22194952, 2011). "A variation in the percentage of tumour cells in the samples could not explain the lack of detection of EGFR mutations in our series based on the 5% sensitivity threshold of our HRM test." (PMID 22192147, 2011). "Identification of somatic mutations in exons coding for tyrosine kinase domain of EGFR in tumours from patients with NSCLC and their association with response with targeted therapies, has led to the introduction of mutational screening of tumours in the clinic." (PMID 21575252, 2011). "There is precedence in that mutations in both ras and EGFR in NSCLC have recently been used in the clinical setting to predict outcome; in fact, patients whose tumours show K-ras mutations, with or without increased EGFR copy number, have been shown to have a >96.5% chance of disease progression." (PMID 21285982, 2011). "Thus, immunodeficient rodents used for the heterotopic propagation and serial passaging of GBM can be considered as reservoirs for providing a continuing supply of the same tumor for establishing orthotopic model that retains the EGFR gene alteration when compared with previous reported methods." (PMID 21314332, 2011). "In addition, Aptamer E07 is readily internalized into EGFR-expressing cells, raising the possibility that it might be used to escort other anti-tumor or contrast agents." (PMID 21687663, 2011). "Here we analyze different pieces of data from mechanistic and clinical studies with the anti-EGFR monoclonal antibody Nimotuzumab, which provides several clues to understand how this antibody may induce a biological control of tumor growth while keeping a low toxicity profile." (PMID 24212794, 2011). "However, EGFR and ras mutations are not a common feature of many tumours; our data strongly suggest that ALKBH3 would be an important marker and target in a wide range of cancers." (PMID 21285982, 2011). "We screened 236 clinical tumor samples from European patients with advanced CRC by direct DNA sequencing to detect potential, as yet unknown mutations, in the EGFR gene exons 18 to 21, mainly covering the EGFR TK catalytic domain." (PMID 22026926, 2011). "Indeed, given that administration of different agents targeting similar signaling pathways in combination with chemotherapy can result in dissimilar outcomes, it is likely that only a specific anti-VEGF/anti-EGFR/chemotherapy combination will be effective against a particular tumor type." (PMID 21559248, 2011). "Thus, in this study, we attempted to determine significant factors related to ECS: multivariate logistic regression analysis revealed that number of pathologically positive lymph nodes and presence of EGFR numerical aberrations of the primary tumour were significantly independent predictors." (PMID 21304522, 2011). "Notably, tumors with the enhanced expression of HOX genes, high EGFR expression plus unmethylated MGMT were associated with short survival, suggesting the involvement of a tumor stem-cell phenotype in the escape of tumor cells from radio-chemotherapy." (PMID 24212792, 2011). "Interestingly, when we restricted the analysis to EGFR-overexpressing tumours (EGFRhigh), we could identify a 79 gene signature distinguishing mutated from non mutated samples." (PMID 21266046, 2011).
tumor (continued). "Given that in vivo overexpression of Tgf-α in mice is clearly pro-oncogenic in the context of wild-type Egfr, leading to pancreatic hyperplasia and mammary epithelial carcinogenesis, expression of EGF family ligands may be one of the keys to our understanding of tumor sensitivity to EGFR inhibitors." (PMID 20975924, 2010). "Retrospective, subset analyses of tumor tissue samples from small clinical trials have demonstrated that tumor KRAS gene mutations are associated with lack of response to both of the EGFR-targeted monoclonal antibodies approved for use in colorectal cancer, cetuximab and panitumumab." (PMID 20877448, 2010). "Since NSCLC clinically are responsive to TKI therapy and given the in vitro response of the MPM mutations to Erlotinib, there may be a role for EGFR-TKI therapy in MPM EGFR mutant patients who develop disease recurrence or present with bulky unresectable tumor." (PMID 20942962, 2010). "Furthermore, the high percentage of tumours expressing both EGFR and VEGF suggests that patients with this rare cancer may benefit from therapeutic strategies targeting EGFR and VEGF receptor (VEGFR)." (PMID 19935793, 2010). "This might be explained by the absence of an activating EGFR mutation, which is a striking predictor for sensitivity of tumour cells to EGFR targeting therapy." (PMID 20683448, 2010). "For example the mutational status of EGFR can be readily detected in primary tumors and the correlation between EGFR mutations and EGFR TKI (Tyrosine Kinase Inhibitors) sensitivity has been validated in several clinical trials, but it may be difficult to obtain tumor tissues for such analysis." (PMID 21532835, 2010). "EGFR targeting agents might have limited roles in this rare tumor." (PMID 20961443, 2010). "Interestingly, both tumour cells and EGFR-expressing endothelial cells were induced to undergo apoptosis by the agent, suggesting that inhibition of angiogenesis may contribute to the efficacy of the drug." (PMID 20010942, 2010). "Whether this reflects a true loss of EGFR receptor or a selection of EGFR-negative tumour cells remains to be investigated." (PMID 20683448, 2010). "However, it is now clearly demonstrated that patients with a tumor KRAS mutation are resistant to anti-EGFR antibodies and do not benefit from this targeted therapy." (PMID 19785749, 2009). "The report on KRAS status in patients with metastatic CRC receiving epidermal growth factor receptor (EGFR) targeted antibody treatment has led to a change in National Comprehensive Cancer Network guideline that recommends only patients with wild-type KRAS tumor should receive this treatment." (PMID 19236713, 2009). "Therefore, blocking EGFR along with conventional cancer therapies could be an attractive anti-tumor strategy." (PMID 19878607, 2009). "In addition, radiation therapy may enhance the EGFR intracellular activation pathways after irradiation, which in turn may contribute to enhance the tumour invasiveness." (PMID 19293809, 2009). "In bivariable analysis with TLE3+, only tumor size trended toward an independent association with outcome in taxane-treated patients whereas age, node status, pathologic grade, and Ki67 and epidermal growth factor receptor (EGFR) expression were not significant." (PMID 19309506, 2009). "Tumor cells may be targeted by inhibiting the epidermal growth factor (EGFR)." (PMID 19657384, 2009).
tumor (continued). "Moreover, because cell surface clustering of a variety of receptors, including EGFR, has been shown to augment receptor function, we hypothesized that α6β4 integrin-induced EGFR clustering might augment particular tumor cell responses to EGF." (PMID 19470173, 2009). "Also, the response rate was higher when 10 percent or more of tumor cells expressed EGFR." (PMID 19159467, 2009). "Hence, the choice of the route of DNA immunizations and formulation of DNA could thus represent an important element in the design of EGFR DNA vaccine against EGFR-positive tumor." (PMID 19178753, 2009). "EGFR and erb-B2 were expressed in 34% and 17% of the specimens, but the authors could not demonstrate any association between EGFR expression or erbB2, and tumour depth, lymph node status, extracapsular invasion, recurrence, or survival." (PMID 19696947, 2009). "Thus, increased EGFR expression and signalling with androgen deprivation may be responsible for the transition of tumours from androgen dependence to androgen independence." (PMID 19888222, 2009). "Patients with KRAS-mutant tumours treated with cetuximab in any combination had lower PFS compared with those with KRASWT tumours, results that extend those reported in recent clinical trials and suggest that KRAS mutation may bypass aberrant EGFR signalling." (PMID 19603024, 2009). "Thus, the marked repression of miR-125a-5p after EGFR activation prompted us to investigate whether miR-125a-5p influenced tumor metastasis." (PMID 19702827, 2009). "The ideal 1 and 2 trials demonstrated that EGFR amplification was associated with a higher response to gefitinib than was seen with tumours without EGFR amplification; however, this difference was not statistically significant (n = 90: risk ratio: 29% vs.15%; p = 0.319)." (PMID 19229369, 2009). "However, metastasis might have different molecular patterns with respect to primary tumour, possibly affecting the prediction of EGFR-targeted therapy efficacy." (PMID 19293803, 2009). "However, in PCa, EGFR expression is upregulated, suggesting an increased expression in advanced cancer, and correlated with a high Gleason score and tumour progression from an androgen-dependent to an androgen-independent state." (PMID 19888222, 2009). "While increased levels of EGFR and ErbB3 protein could be detected in the bitransgenic tumours when compared with normal tissue, the extent of the increase was dramatically reduced compared with that observed in the c-ErbB2 tumours." (PMID 18700973, 2008). "However, based on our study results, EGFR mutations, gene copy number, and protein expression does not appear to be associated with the distribution of tumour-associated macrophages." (PMID 18283317, 2008). "Importantly, cortactin and EGFR expression levels observed in the TMA discs faithfully reflected the staining intensity of these proteins in whole-tissue sections from corresponding tumour blocks in a subset of 30 cases (see Materials and Methods section)." (PMID 18268492, 2008). "Interestingly, these radiation-related stimulations of both tumour cell proliferation and tumour angiogenesis were markedly diminished by the presence of the drug combination, with the EGFR-targeting drug probably playing a role in the attenuation of radiation-induced tumour proliferation." (PMID 18577994, 2008). "Furthermore, the expression of phosphorylated EGFR (pY1173-EGFR-positive) on tumour cells from metastatic lesions carrying the T847A and L692P-V717A mutations strongly suggests that the former might be activating EGFR mutation." (PMID 19238633, 2008). "However, we identified a subset of 29 tumours in which cortactin and EGFR overexpression could be uncoupled." (PMID 18268492, 2008). "Thus, EGFR appears to be a necessary element for uPAR-mediated tumor progression." (PMID 18519000, 2008). "None of the nine tumours with KRAS mutations responded to EGFR-TKIs." (PMID 17325698, 2007).
tumor (continued). "Exploring a combination of VDAs and epidermal growth factor receptor (EGFR) inhibitors theoretically could also be an interesting approach; here one could speculate that tumour cells in the viable rim will become apoptotic and die when being deprived of their growth-stimulating factors such as EGF." (PMID 17375046, 2007). "Thus, in addition to direct effects on tumour cells, EGFR-targeting drugs may also impart an indirect antitumour effect through antiangiogenic activity." (PMID 17592499, 2007). "Thus, inhibition of EGFR activity without down-regulation of the receptor could represent a novel therapeutic approach toward malignancies in which EGFR has a primary role promoting tumor growth." (PMID 19662191, 2007). "The model also suggested that the early switching of cells in such aggressive tumors from proliferative to migrating behavior may be the result of EGFR signaling and suggested that proteomics data should be added to transcriptional analysis in making predictive assessments of tumor dynamics." (PMID 19936081, 2007). "It has been shown that the choice of fixative and storage time of tumour tissue, the choice of primary antibody and scoring system, and the lack of standardised criteria for evaluation all represent potential pitfalls and have a substantial impact on determination of EGFR immunoreactivity." (PMID 17940504, 2007). "Furthermore, EGFR is overexpressed in approximately 90–100% of SCCHN specimens and has been associated with worse prognosis, including advanced stage, poorly differentiated tumours and poor survival." (PMID 17224925, 2007). "The patients with EGFR mutations had a longer median OS than the patients without EGFR mutations, but the difference was not statistically significant (716 vs 193 days, P=0.070, in tumour samples; 387 vs 228 days, P=0.489, in serum samples)." (PMID 17848912, 2007). "Importantly, tumor regression has been observed with these agents in patients that did not have identifiable EGFR mutations, suggesting other mechanisms, such as activation of parallel signalling pathways, underlie responsiveness to these agents." (PMID 17096850, 2006). "Therefore, we used the expression of CK5/6 and EGFR to identify basal-like tumours." (PMID 17088909, 2006). "Nuclear FABP7 may be induced by EGFR activation to promote migration of GBM tumor cells." (PMID 16623952, 2006). "First, we could not compare the results of the EGFR mutation status in the pleural effusion fluid to the mutation status in tumour tissue." (PMID 17060940, 2006). "In addition, identifying patients who may clinically benefit from EGFR TKI other than through overt tumor response remains unclear." (PMID 17096850, 2006). "Since EGFR-selective tyrosine kinase inhibitors are typically given to patients who have already been on chemotherapy, the tendency for a recurrent tumor to include less EGFR-positive cells especially if validated in larger series, could influence its sensitivity to this targeted therapy." (PMID 17163999, 2006). "The epidermal growth factor receptor (EGFR) is a transmembrane glycoprotein, which, once activated by a growth stimulus, initiates a signal transduction cascade of biochemical, and physiological changes that culminate in mitogenic signalling and other tumour-promoting cellular activities." (PMID 16570047, 2006). "In previous clinical reports, gefitinib was effective in a few patients without EGFR mutations, thus indicating that not only mutations in TK domain but other mechanisms such as amplification, aberrant signaling may activate AKT and sensitise tumour cells to EGFR inhibitors." (PMID 16552419, 2006). "Therefore, we undertook this study with the hypothesis that a gene expression signature of response will capture more of the variability within the tumor and improve prediction of EGFR TKI sensitivity than currently preferred methods." (PMID 17096850, 2006). "Neither EGFR nor IL8 tumour levels were linked to the differential sensitivity to ZD6126." (PMID 16940984, 2006).
tumor (continued). "As pleural effusion fluid sampling is usually easy, non-invasive, and repeatable, we hypothesised that tumour-derived DNA in the pleural effusion fluid of NSCLC patients would be a source of useful information on the status of the EGFR gene and could allow prediction of the response to gefitinib." (PMID 17060940, 2006). "Furthermore, other components such as EGFR and cyclin D1 could play active roles in tumour response to radiotherapy." (PMID 15956964, 2005). "As only surgically resected tumours were involved in the study, the incidence of EGFR mutations in the study could not indicate the incidence in whole NSCLCs." (PMID 16052218, 2005). "Therefore, in tumour cells that are highly dependent on EGFR signalling for continued proliferation and survival, direct tumour cell effects may contribute significantly to the in vivo antitumour activity of ZD6474." (PMID 15928657, 2005). "Despite only binding ∼10% EGFR on A431 cells the 111In-ch806 demonstrated a mean peak uptake at 3 days of 33%ID g−1 and was highly retained within the tumour over the study period, in marked contrast to 125I-ch806, which showed minimal specific A431 tumour uptake." (PMID 15770208, 2005). "Finally, we looked at EGFR as a marker of tumor growth and progression." (PMID 16026610, 2005). "In addition, cytotoxic T lymphocyte (CTL)-directed epitopes could be another class of compound useful in EGFR-targeted therapies as peptide vaccines for cancer patients whose tumours overexpress EGFR." (PMID 15083186, 2004). "In addition, there is evidence that blocking EGFR could further increase chemo- and radiosensitivity of tumour cells expressing high receptor levels in vitro and in vivo." (PMID 15213712, 2004). "In addition, EGFR contributes to the growth characteristics of NE tumours." (PMID 14583782, 2003). "In addition, it was shown that MAPK pathway status may influence ZD1839 activity only in tumour cells that are strongly dependent upon EGFR signalling (high EGFR content)." (PMID 11986789, 2002). "The pattern and extent of reactivity has been correlated with clinicopathological data including tumour type, grade and lymph node status and with other prognostic parameters including oestrogen receptor (ER) status, expression of c-erbB-2, pS2 protein and epidermal growth factor receptor (EGFR)." (PMID 8883410, 1996). "In order to determine whether genetic alterations might be of help in subdividing this group, we used allele loss on chromosomes 10 and 17p and epidermal growth factor receptor (EGFR) gene amplification in the tumours as genetic parameters and determined their prognostic value." (PMID 7917918, 1994). "Proteogenomic investigations in CCA have identified novel isoforms of critical signaling proteins, including FGFR2 and EGFR, which are often modified in CCA and are integral to tumor growth and drug resistance." (PMID 41562920, 2026). "Here we report that GLDC is polyubiquitinated at K636 following EGFR activation, which drives GLDC-dependent transcriptional inhibition of MHC-I genes and induces tumor cells to evade CD8+ T cell-mediated immunosurveillance." (PMID 41728086, 2026). "For example, SOX2 sustains tumor stemness to promote chemotherapy resistance, SOX4 modulates EMT and angiogenesis and SOX9 collaborates with EGFR/KRAS signaling pathways to drive tumor invasion." (PMID 41268614, 2026). "NOX4 has been shown to mediate resistance to EGFR-targeted therapies, while both EGFR and PDGFR are critical in signaling pathways that drive tumor growth and metastasis." (PMID 41562694, 2026). "Receptor tyrosine kinases (RTKs), including VEGFR-2, EGFR, and c-MET, have been recognized as promising oncogenic targets in tumor progression, invasion, and metastasis." (PMID 41658091, 2026).